HACD4 (3-hydroxyacyl-CoA dehydratase 4)
Description:
Catalyzes the third of the four reactions of the long-chain fatty acids elongation cycle. This endoplasmic reticulum-bound enzymatic process, allows the addition of two carbons to the chain of long- and very long-chain fatty acids/VLCFAs per cycle. This enzyme catalyzes the dehydration of the 3-hydroxyacyl-CoA intermediate into trans-2,3-enoyl-CoA, within each cycle of fatty acid elongation. Thereby, it participates in the production of VLCFAs of different chain lengths that are involved in multiple biological processes as precursors of membrane lipids and lipid mediators.
Synonyms: PTPLAD2; Em:AL662879.1; OTTHUMG00000021016
Tractability: Antibody: UniProt predicts a signal peptide or a membrane-spanning region.
Gene: Protein-coding gene on chromosome 9 (20,999,509 to 21,031,640, reverse strand). Ensembl gene ENSG00000188921.
Subcellular location: Endoplasmic reticulum membrane
Pathways (Reactome):
Metabolism: Synthesis of very long-chain fatty acyl-CoAs
Gene Ontology:
Molecular function: enzyme binding; protein binding; very-long-chain (3R)-3-hydroxyacyl-CoA dehydratase activity; (2E)-enoyl-CoA hydratase activity
Biological process: fatty acid elongation; very long-chain fatty acid biosynthetic process; sphingolipid biosynthetic process; fatty acid biosynthetic process
Cellular component: endoplasmic reticulum; endoplasmic reticulum membrane
Genetic constraint (gnomAD): Loss-of-function variants: 15 observed, 12.45 expected, observed/expected ratio (o/e) 1.2, 90% interval 0.8 to 1.78. The upper end of that interval is the gene's LOEUF score, 1.78, which puts it in group 6 of 6, group 1 being the genes least tolerant of losing a copy. Missense variants: 141 observed, 114.88 expected, observed/expected ratio (o/e) 1.23, 90% interval 1.07 to 1.41. Synonymous variants: 48 observed, 43.37 expected, observed/expected ratio (o/e) 1.11, 90% interval 0.88 to 1.41.
Homologues: Orthologues: chimpanzee HACD4 (99% identical), macaque HACD4 (99% identical), pig HACD4 (94% identical), dog HACD4 (92% identical), guinea pig HACD4 (89% identical), rat Hacd4 (88% identical), mouse Hacd4 (85% identical), rabbit HACD4 (78% identical), tropical clawed frog hacd4 (55% identical), zebrafish hacd4 (39% identical), Drosophila melanogaster Hacd2 (30% identical), Caenorhabditis elegans R10E4.9 (20% identical). Paralogues in human: HACD3 (41% identical), HACD2 (27% identical), HACD1 (22% identical).
Diseases named in the same sentence as HACD4 in open-access papers:
HACD4 is named in the same sentence as 7 diseases in open-access papers, as found by Europe PMC text mining. Sharing a sentence is not in itself a finding about the gene and the disease. The quoted sentences say what the papers report.
atherosclerosis (1 paper, 2024). A disease characterized by the build-up of fatty material and calcium deposition in the arterial wall resulting in partial or complete occlusion of the arterial lumen. "HACD4 is a protein-coding gene involved in the biosynthesis and metabolism of fatty acyl-CoA, which is mainly associated with spinocerebellar ataxia and atherosclerosis in men32." (PMID 38839927, 2024).
COVID-19 (1 paper, 2021). A disease caused by infection with severe acute respiratory syndrome coronavirus 2. "The CD16+ monocytes in the mild COVID-19 group expressed higher levels of glycolysis-related genes (PGAM1 and GAPDH), a fatty acid-related gene (HACD4), and an arginine and proline metabolism-related gene (SAT2), as well as lower levels of a cysteine and methionine metabolism-related gene (AHCYL1)." (PMID 33936072, 2021).
leukemia (1 paper, 2023). A malignant (clonal) hematologic disorder, involving hematopoietic stem cells and characterized by the presence of primitive or atypical myeloid or lymphoid cells in the bone marrow and the blood. "We identified recurrently affected genes by SVs, such as FOCAD/HACD4, MANBA, and SFMBT2 that were validated by long-read sequencing and/or RNA-seq in at least 1 leukemia." (PMID 37469802, 2023).
Obesity (1 paper, 2020). Accumulation of substantial excess body fat. "Several obesity- and lipid-metabolism-related genes were differentially expressed in the testis of obese rats, including fatty acid synthesis, such as acyl-CoA thioesterase 4 (O/C −10.75) or fatty acid elongation, including 3-hydroxyacyl-CoA dehydratase 4 (O/C 4.81)." (PMID 32899471, 2020).
squamous carcinoma (1 paper, 2025). "Protein tyrosine phosphatase-like A domain-containing 2 (HACD4/PTPLAD2) is a potential tumor suppressor in squamous carcinoma responsible for the inhibition of STAT3 phosphorylation." (PMID 39985075, 2025).
tumor (3 papers, 2019 to 2025). "By integrating both single-cell and bulk RNA-seq data, we identified six key prognostic genes (BOP1, CTBP1, DSE, PMSD10, SRPK1, and HACD4), which were associated with poor prognosis and tumor cell proliferation." (PMID 40963856, 2025). "The analysis revealed that risk genes (BOP1, CTBP1, DSE, SRPK1, and PMSD10) were significantly upregulated in tumor samples, whereas the protective gene HACD4 was highly expressed in normal samples." (PMID 40963856, 2025).
HACD4 also shares sentences with these, for which no sentence is quoted: spinocerebellar ataxia (1 paper).